WASHC2C (WASH complex subunit 2C)
Description:
Acts as a component of the WASH core complex that functions as a nucleation-promoting factor (NPF) at the surface of endosomes, where it recruits and activates the Arp2/3 complex to induce actin polymerization, playing a key role in the fission of tubules that serve as transport intermediates during endosome sorting. Mediates the recruitment of the WASH core complex to endosome membranes via binding to phospholipids and VPS35 of the retromer CSC. Mediates the recruitment of the F-actin-capping protein dimer to the WASH core complex probably promoting localized F-actin polymerization needed for vesicle scission. Via its C-terminus binds various phospholipids, most strongly phosphatidylinositol 4-phosphate (PtdIns-(4)P), phosphatidylinositol 5-phosphate (PtdIns-(5)P) and phosphatidylinositol 3,5-bisphosphate (PtdIns-(3,5)P2). Involved in the endosome-to-plasma membrane trafficking and recycling of SNX27-retromer-dependent cargo proteins, such as GLUT1. Required for the association of DNAJC13, ENTR1, ANKRD50 with retromer CSC subunit VPS35. Required for the endosomal recruitment of CCC and retriever complexes subunits COMMD1 and CCDC93 as well as the retrievere complex subunit VPS35L. (Microbial infection) Plays a role in fluid-phase endocytosis, a process exploited by vaccinia intracellular mature virus (IMV) to enter cells. As a result, may facilitate the penetration of IMV into cells.
Synonyms: VPEF; FAM21C; KIAA0592; FAM21A
Tractability: Antibody: UniProt places it where antibodies can reach, with medium confidence; its Gene Ontology location is reachable by antibodies, with medium confidence. PROTAC: ubiquitination databases record sites on it.
Gene: Protein-coding gene on chromosome 10 (45,727,193 to 45,792,964, forward strand). Ensembl gene ENSG00000172661.
Subcellular location: Early endosome membrane; Cell membrane
Subcellular location (Human Protein Atlas): Vesicles; Cytosol; Nucleoli
Gene Ontology:
Molecular function: phosphatidylinositol-3,4,5-trisphosphate binding; phosphatidylinositol-3,4-bisphosphate binding; phosphatidylinositol-3,5-bisphosphate binding; phosphatidylinositol-3-phosphate binding; phosphatidylinositol-4,5-bisphosphate binding; phosphatidylinositol-4-phosphate binding; phosphatidylinositol-5-phosphate binding; protein binding; retromer complex binding; phosphatidylinositol phosphate binding
Biological process: endocytic recycling; negative regulation of barbed-end actin filament capping; protein localization to endosome; regulation of substrate adhesion-dependent cell spreading; retrograde transport, endosome to Golgi; endosomal transport; regulation of Arp2/3 complex-mediated actin nucleation
Cellular component: early endosome; early endosome membrane; endosome; WASH complex; cytosol; plasma membrane
Genetic constraint (gnomAD): Loss-of-function variants: 70 observed, 112.49 expected, observed/expected ratio (o/e) 0.62, 90% interval 0.51 to 0.76. The synonymous counts are far from expectation, so gnomAD's model fits this gene poorly and the ratio says little. Missense variants: 910 observed, 1,252.7 expected, observed/expected ratio (o/e) 0.73, 90% interval 0.69 to 0.77. Synonymous variants: 307 observed, 446.16 expected, observed/expected ratio (o/e) 0.69, 90% interval 0.63 to 0.76.
Homologues: Orthologues: chimpanzee WASHC2A (98% identical), dog WASHC2C (80% identical), mouse Washc2 (74% identical), rat Washc2c (73% identical), Drosophila melanogaster FAM21 (21% identical), zebrafish washc2c (16% identical). Paralogues in human: WASHC2A (99% identical), RCSD1 (7% identical).
Diseases named in the same sentence as WASHC2C in open-access papers:
WASHC2C is named in the same sentence as 4 diseases in open-access papers, as found by Europe PMC text mining. Sharing a sentence is not in itself a finding about the gene and the disease. The quoted sentences say what the papers report.
infection (2 papers, 2020 to 2024). The state of being infected such as from the introduction of a foreign agent such as serum, vaccine, antigenic substance or organism. "Our association data suggests that WASHC2C is modulated late in infection." (PMID 32041945, 2020). "pUL26 and pUL99 levels were not decreased, suggesting WASHC2C has a role late in infection (after viral protein production), likely in intracellular trafficking events." (PMID 32041945, 2020).
WASHC2C also shares sentences with these, for which no sentence is quoted: hepatocellular carcinoma (2 papers); cancer (1); tumor (1).